IL6 (interleukin 6)
Diseases named in the same sentence as IL6 in open-access papers (continued):
Sharing a sentence is not in itself a finding about the gene and the disease.
Hyperglycemia (continued). "A recent study showed IL-6 is also a key factor in promoting gluconeogenesis, and endocrine IL-6 is a directive signal necessary to mediate hyperglycemia through hepatic gluconeogenesis during stress." (PMID 36447227, 2022). "Hyperglycaemia induction by STZ resulted in a significant increase of IL6 levels (81.6 ± 0.75 pg/ml) (P<0.05) compared to the negative control group (32.28 ± 3.3 pg/ml)." (PMID 35802659, 2022). "Periodontal disease has been associated to the generation of proinflammatory mediators connected to hyperglycemia (IL-6, TNF-α, and CRP)." (PMID 36557312, 2022). "Decreased insulin sensitivity and increased glucose production lead to decreased islet cell function and hyperglycemia, as well as increased release of inflammatory factors (such as IL-6, TNF-α, and C-reactive protein)." (PMID 35432188, 2022). "Under hyperglycemia, the production of IL-1β, IL-6, and TNF-α is promoted, thereby accelerating the apoptosis of islet β cells and inducing islet failure." (PMID 35845591, 2022). "It has been reported that hyperglycemia increases advanced glycationend product formation and reactive oxygen species (ROS) and activates NF-κB, followed by an increase in cytokines (IL-1, IL-6, TNF-α)." (PMID 36406423, 2022). "Higher levels of IL-6 in patients with hyperglycemia or elevated blood sugar were observed on admission." (PMID 35989853, 2022). "It was also found that hyperglycemia suppressed IL-2, IL-6 and IL-10 in peripheral blood mononuclear cells (PBMCs) suggesting impaired cellular defense mechanism in patients with diabetes." (PMID 35957811, 2022). "Uric acid significantly increased the expression of IL-6, IL-8 and IL-1β mRNAs when compared with hyperglycaemia alone, which itself induced a significant pro-inflammatory response." (PMID 35503137, 2022). "Hyperglycemia decreases H3K9me3 at the IL-6 promoter in human monocytes, thereby increasing IL-6 expression." (PMID 35603204, 2022). "In an in vivo study, BAY 11–7082 (a selective NF-κB inhibitor) protects rats from diabetic nephropathy through decreasing the expression of inflammatory factors such as TNF-α and IL-6 and suppressing the oxidative damage regulated by hyperglycaemia." (PMID 35251212, 2022). "Poor periodontal status in proportion to poor glycemic control is a result of hyperglycemia-induced accelerated expression of inflammatory mediators such as Interleuikin-6 (IL-6), Tumor necrosis factor-Alpha (TNF-α), and toll-like receptors." (PMID 36557041, 2022). "Nevertheless, proinflammatory cytokine IL-18 was reported to be elevated in newly diagnosed T2DM and prediabetic patients, and acute hyperglycemia was shown to induce the increase in plasma IL-6, TNF-α, and IL-18 concentrations." (PMID 36547931, 2022). "Of note, patients presenting with hyperglycemia were those with the highest levels of IL-6, reinforcing the notion that hyperglycemia and inflammation are closely intertwined." (PMID 35329890, 2022). "Hyperglycemia increased IL-6 levels in human RMCs and the activation of IL-6 in the early stages induced the production of VEGF-A to protect RMCs from high glucose toxicity." (PMID 36531955, 2022). "In the present study, the production of ROS and mRNA expression levels of Il6, an inflammatory cytokine, were significantly increased under hyperglycemia in rat Achilles tendon-derived cells." (PMID 35689230, 2022). "The persistent hyperglycaemia can alter the release and functionality of inflammatory cytokines like interleukin 1 (IL-1), interleukin 6 (IL-6) and tumour necrosis factor-a (TNF-a), leading to an increase in T2DM." (PMID 36419622, 2022). "We demonstrated that psoriasin was upregulated on both mRNA and protein levels, confirming the interrelationship between IL-6 and psoriasin also during hyperglycemia." (PMID 36127330, 2022).
Hyperglycemia (continued). "We also found that blood glucose level was positively correlated with the serum concentration of IL-6 and CRP level, suggesting that hyperglycemia aggravated the systemic inflammatory response caused by SARS-CoV-2." (PMID 37359706, 2022). "Proinflammatory cytokines IL-1β, IL-6, IL-18, and TNFα which play major roles in the development and progression of DN are triggered by hyperglycemia and oxidative stress." (PMID 33562428, 2021). "IL-6 mRNA levels were slightly increased in H6c7-pBp cells by hyperglycemia, whereas the presence of macrophages led to decreased mRNA levels under normoglycemic conditions after 2 days." (PMID 34064969, 2021). "Studies have revealed that hyperglycemia stimulates a reversible increase in the concentrations of IL-6 and decline in histone-3 methylation at the IL-6 promoter in cardiomyocytes." (PMID 33639960, 2021). "Hyperglycemia-induced production of interleukin-1β (IL-β), interleukin-6 (IL-6), tumor necrosis factor-α (TNF-α), and chemokine ligand-2 (CCL2) by Müller cells is linked to retinal cell death." (PMID 33875782, 2021). "Both in vitro and in vivo studies have linked hyperglycaemia with elevated levels of C-reactive protein (CRP), interleukin-6 (IL-6), and TNF-α." (PMID 33466656, 2021). "IL-6 values changes were significant between the normoglycemia and hyperglycemia groups and within the variable for each group." (PMID 34117510, 2021). "In H6c7-kras cells, the presence of macrophages had a stronger effect on IL-6 expression than hyperglycemia." (PMID 34064969, 2021). "In the hyperglycemia group, serum concentrations of IL-6 at baseline, at 24 h and 48 h post-trauma, were significantly higher than those of the normoglycemia group." (PMID 34117510, 2021). "The IL-6 levels were significantly decreasing as time increasing for both the groups (p < 0.05), and the variable values were statistical more in the hyperglycemia than the normoglycemia group at each point of time (p < 0.05)." (PMID 34117510, 2021). "Following Tocilizumab administration, IL-6 levels decreased in both groups, but remained higher in the hyperglycaemia group." (PMID 34201473, 2021). "Hyperglycaemia in diabetic patients increases proinflammatory cytokines (interleukin-1 and interleukin-6), which induce osteocytes to produce sclerostin." (PMID 34690653, 2021). "Patients presented with hyperglycemia were more likely to have higher levels of IL-6, IL-18 and hs-CRP compared to the normoglycemic patients." (PMID 34117510, 2021). "Hyperglycemia activates the production of multiple proinflammatory cytokines (e.g., IL-1, IL-6, and TNFα) and leads to the recruitment of inflammatory cells to the kidney." (PMID 34200774, 2021). "TNF-α and IL-6 are important inflammatory cytokines whose secretion can be stimulated by hyperglycaemia, hyperlipidaemia and other metabolic abnormalities." (PMID 33050458, 2020). "The quercetin administration or treatment with both doses of PhyF extract reduced the IL-6 levels in normoglycemia (p < 0.001), while, in hyperglycemia, the protective effect was exerted only by 0.1 and 0.05 μg GAE/mL PhyF extract (p < 0.001)." (PMID 32824505, 2020). "Systematically, hyperglycemia causes AGE formation and increases ROS product and plasma proinflammatory cytokines, including TNF-α and interleukin-6 (IL-6)." (PMID 33013692, 2020). "In a mouse model of nonmetastatic breast cancer, we demonstrated that tumor-bearing mice displayed systemic IL-6 driven inflammation concomitant with hyperglycemia/insulinemia." (PMID 32193527, 2020). "Hyperglycemia leads to increased inflammatory cytokines of renal tubular epithelial cells and these inflammatory cytokines, such as IL-1, IL-6, IL-18, and TNF-α can directly damage renal tubular cells." (PMID 32073611, 2020). "To obtain more comprehensive details about the inflammatory processes caused by hyperglycemia, we examined the expression of TNF-α, IL-6, IL-8, and IL-1α." (PMID 33147748, 2020).
Hyperglycemia (continued). "Hyperglycemia induced a proinflammatory status, an effect proved by the increase of IL-6 secretion (p < 0.05)." (PMID 32824505, 2020). "Triggered by hyperglycaemia, the release of IL-6 in podocytes, mesangial cells and tubule cells contributes to and sustains local and systemic subclinical inflammation." (PMID 31001673, 2019). "Other data show that as hyperglycemia increases, various cytokines (including IL-6) are augmented and a number of growth factors including vascular endothelial growth factor (VEGF) and placental growth factor (PlGF) are inhibited." (PMID 31647034, 2019). "Previous studies also demonstrated that advanced glycosylation ends triggered by long-term hyperglycemia can stimulate phagocytes to release inflammatory cytokines, including tumor necrosis factor, IL-1β, and IL-6." (PMID 31209719, 2019). "Long-time hyperglycemia and aging increase production of inflammatory factors, such as IL-6, TNF-α, and CRP, which promote the onset of DPN." (PMID 31781662, 2019). "Hyperglycemia increases the level of proinflammatory cytokines, such as interleukin (IL)-1β, IL-2, and IL-6 in the serum of DM patients and has been reported by several studies." (PMID 31514311, 2019). "Hyperglycemia increases the expression of pro-inflammatory cytokines such as IL-6, IL-1β, TNF-α, and TGF-β." (PMID 31736745, 2019). "Real-time PCR demonstrated that ARPE-19 cells responded to either cytokines or hyperglycemia by upregulating proinflammatory genes such as cytokines (IL-1β and IL-6) and chemokines (CCL2, CCL5) as well as VEGF, an established inducer of vascular leakage." (PMID 31344857, 2019). "As SOCS-3 is upregulated in this study, this confirms the inflammatory effect of IL-6 in hyperglycemia." (PMID 31415598, 2019). "Of note, FGF21 has been shown to reduce levels of inflammatory mediators including IL-1β, IL-6 and TNFα in the serum of obese/diabetic db/db mice and ameliorates hyperglycemia." (PMID 31312114, 2019). "Further, hyperglycemia itself can reproduce these effects in keratinocyte cultures where IL-6-induced p-STAT3 levels are increased compared to control." (PMID 31073533, 2019). "Heme oxygenase 1 overexpression suppresses hyperglycemia-induced gene expression of IL1β, IL6, and MCP1." (PMID 31616304, 2019). "Treatment of Nrf2 activator DMF (HG/DMF) partly restored hyperglycemia-induced IL6 secretion, while it completely restored the secretion of IL1β and MCP1 compared to the HG/VEH group." (PMID 31616304, 2019). "Treatment of Nrf2 activator DMF (HG/DMF) partly restored hyperglycemia-induced expression of IL1β and IL6, while it completely restored MCP1 expression compared to the HG/VEH group." (PMID 31616304, 2019). "Next, hyperglycemia contributes to increased expression of IL-6 and TGF-β that synergistically down regulate FoxP3 at the post-translational level by promoting FoxP3 protein degradation in Tregs." (PMID 30804929, 2019). "One particular study has shown hyperglycemia to stimulate the synthesis and production of IL-6 by human peripheral blood monocytes in vitro." (PMID 31396410, 2019). "Long-term hyperglycemia leads to the production of a wide range of pro-inflammatory factors, such as interleukin-6 (IL-6), tumor necrosis factor-α (TNF-α), cyclooxygenase-2 (COX-2)." (PMID 31337431, 2019). "It has been previously reported that hyperglycemia-induced TLR-4 stimulation creates an inflammatory milieu, and causes recruitment of monocytes, hence stimulates IL-6 secretion." (PMID 30534206, 2018). "In our study administration of STZ results in hyperglycemia and severe oxidative stress, followed by inflammation, that was evidenced by the changes in the cytokines like IL-6, NF-kB, and TNF-α related to inflammation." (PMID 29670899, 2018). "In summary, our observations demonstrate that the activation of either IL‐6 classic or trans‐signalling advances podocyte harming under hyperglycaemia." (PMID 28881473, 2018).
Hyperglycemia (continued). "BAY 11-7082 protects rats from DN by reducing the expression of inflammatory cytokines including TNF-α, IL-1β, and IL-6, and inhibiting the oxidative damage mediated by hyperglycemia." (PMID 30459606, 2018). "Our observations demonstrate that both IL‐6 classic signalling and trans‐signalling accelerate podocyte and glomeruli damage during hyperglycaemia." (PMID 28881473, 2018). "We found that exhaustive, but not moderate exercise, immediately prior to treatment, prevented olanzapine-induced hyperglycemia and this occurred in parallel with increases in serum IL-6." (PMID 29335597, 2018). "Further, we aimed to assess the role of IL-6 with respect to exercise, as a mechanism to offset olanzapine-induced hyperglycemia." (PMID 29335597, 2018). "In the present study, the beneficial effects from allicin on DN were shown, including attenuation of hyperglycemia, oxidative stress and inhibition of inflammation through the down-regulation of NFκβ/Iκβ and its target genes IL-1 and IL-6." (PMID 30314265, 2018). "Despite the lack of a genotype effect with exercise in protecting against olanzapine-induced hyperglycemia there were differences between WT and IL-6−/− mice with regards to serum insulin concentrations." (PMID 29335597, 2018). "Having shown that exhaustive exercise protects against olanzapine-induced hyperglycemia in parallel with increases in IL-6 we wanted to examine if increases in IL-6 were sufficient to protect against increases in blood glucose following olanzapine treatment." (PMID 29335597, 2018). "Although exhaustive exercise protected against olanzapine-induced hyperglycemia in IL-6−/− mice, we found that exercise-induced increases in serum insulin from olanzapine compared to vehicle treated animals were absent." (PMID 29335597, 2018). "High GI diets induce hyperglycemia, which in turn induces oxidative stress and increases pro-inflammatory cytokines, including IL-6 and TNF-α, among both healthy subjects and those with impaired glucose tolerance." (PMID 29414858, 2018). "Entering into the merits of the discussion, IL6 is a complex protein and an inflammatory marker related to oxidative stress, and induced by hyperglycemia." (PMID 30246793, 2018). "STAT3 is the major downstream signalling of IL‐6 and plays an essential role in hyperglycaemia‐initiated glomerular and podocyte injury." (PMID 28881473, 2018). "Further characterization of the inflammatory response to hyperglycemia, as well as nerve degeneration, is required to validate the role of other key cytokines important in corneal homeostasis, including IL-1α and IL-6." (PMID 30470798, 2018). "Taken together, our study demonstrated that both the IL‐6 classic signalling and trans‐signalling are activated and play a detrimental role in podocyte injury during hyperglycaemia via STAT3 Tyr 705 phosphorylation." (PMID 28881473, 2018). "For example, the activation of NF-κB and release of TNF-α and IL-6 in human monocytes in response to hyperglycemia were suppressed by 3–10 mM luteolin." (PMID 28740538, 2017). "Of note, hyperglycemia also increased pancreatic expression of IL-6 and IFN-γ, indicators of inflammation, leading to pancreatic apoptosis as shown by the increase in Bax, cleaved caspase-3 protein expression and the Bax/Bcl-2 ratio." (PMID 29051569, 2017). "Further, liraglutide treatment significantly suppressed the hyperglycemia-enhanced vascular expression of Il-1, Tnf-α, and Tgf-β, and tended to reduce Il-6 and Mcp-1 levels." (PMID 28969637, 2017). "We show that short‐term hyperglycemia decreases IL‐6 expression in CD14++CD16+ intermediate monocytes and IL‐17A expression." (PMID 27042306, 2016). "An RNA‐seq analysis of whole blood RNA demonstrated alterations in multiple immune pathways and transcripts during acute hyperglycemia including decreased transcription of IL‐6, an important component of both innate and adaptive immune responses." (PMID 27042306, 2016).
Hyperglycemia (continued). "An increased secretion of TNF-α and IL-6 under conditions of hyperglycemia is a finding observed by several authors." (PMID 26861982, 2016). "Previous studies have described immune responses during acute hyperglycemia and have focused on expression of IL‐6." (PMID 27042306, 2016). "Second, increased levels of IL-1beta and IL-6 were observed in db/db mice prior to hyperglycemia or substantial differences in weight (<10%) compared to control mice." (PMID 27843953, 2016). "Using THP‐1 cell lines, investigators have shown that in vitro hyperglycemia increased IL‐6 expression." (PMID 27042306, 2016). "At the end of 24 hr, hyperglycemia augmented the mRNA expressions of interleukin (IL)-1β and IL-6 in the MLNs, while both the helper T (Th) 2 and regulatory-T (Treg) transcriptional factors were simultaneously up-regulated under non-endotoxemic condition." (PMID 26207186, 2015). "The proinflammatory cytokine IL-6 is normally released upon infection; however, it induces insulin resistance during conditions of hyperglycemia." (PMID 24899891, 2014). "Hyperglycemia resulting from impaired secretion and/or action of insulin acts on bone tissue cells through an increased production of interleukin-6 (IL-6) in osteoblast line cells." (PMID 25050121, 2014). "Results showed that the hyperglycemia-induced GAG alterations in the cell surface perlecan as well as in the ECM indeed upregulated the expressions of IL-6, IL-8, and MCP-1 and the activities of MMP-2 and MMP-9 and downregulated the expressions of TIMP-2." (PMID 23983782, 2013). "Conversely, when insulin secretion is suppressed, acute hyperglycemia during intravenous glucose administration increases plasma IL-6 concentrations." (PMID 23776669, 2013). "First, although we found correlation between a high IL-6 level and hyperglycemia in the present study, it is difficult to elucidate the interaction between high IL-6 level and hyperglycemia." (PMID 22494810, 2012). "High blood IL-6 level was correlated with hyperglycemia and with difficulties in glucose control in septic patients." (PMID 22494810, 2012). "• In septic patients, a high IL-6 level, which is an index of hypercytokinemia, correlated with hyperglycemia and difficulties in glucose control." (PMID 22494810, 2012). "Circulating levels of TNF-α, IL-6 and nitrotyrosine were consistently and time-dependently elevated after postchallenge hyperglycemia." (PMID 22397368, 2012). "Future study is indicated to validate the antioxidant/anti-inflammatory strategy targeting on interleukin-6 for endothelial protection in in vivo and clinical hyperglycemia." (PMID 22553973, 2012). "Hyperglycemia and hyperinsulinemia have each been shown to raise plasma IL-6 levels, although with different response times." (PMID 22347395, 2012). "We have recently shown that hyperglycemia induces proinflammatory cytokine release (IL-1, IL-6, and TNF-α) in monocytes via an NF-κB-dependent pathway." (PMID 23320034, 2012). "Animals with MS present a dysregulation in the feedback mechanism between IL-6 and NA which can contribute to the systemic low-grade inflammation and/or hyperglycaemia of MS." (PMID 21599899, 2011). "After endotoxin stimulation, the induction of hyperglycemia led to a slight but significant increase in IL-6 in healthy volunteers, whereas TNF-α levels were unaffected." (PMID 18710523, 2008). "Hyperglycemia enhances plasma levels of interleukin (IL)-6 and tumor necrosis factor-alpha (TNF-α) in normal healthy volunteers." (PMID 18710523, 2008). "Hyperglycemia has been shown to increase the release of pro-inflammatory mediators such as IL-6, IL-8, and TNF, which are important in inflammation." (PMID 16999863, 2006). "Patients with hyperglycemia on admission to the ICU had increased levels of IL-6 and IL-10, although after multivariate analysis only IL-6 was associated with hyperglycemia." (PMID 16356228, 2005).